CASK (calcium/calmodulin dependent serine protein kinase)
Description:
Multidomain scaffolding Mg(2+)-independent protein kinase that catalyzes the phosphotransfer from ATP to proteins such as NRXN1, and plays a role in synaptic transmembrane protein anchoring and ion channel trafficking. Contributes to neural development and regulation of gene expression via interaction with the transcription factor TBR1. Binds to cell-surface proteins, including amyloid precursor protein, neurexins and syndecans. May mediate a link between the extracellular matrix and the actin cytoskeleton via its interaction with syndecan and with the actin/spectrin-binding protein 4.1. Component of the LIN-10-LIN-2-LIN-7 complex, which associates with the motor protein KIF17 to transport vesicles containing N-methyl-D-aspartate (NMDA) receptor subunit NR2B along microtubules (By similarity).
Synonyms: hCASK; LIN2; CAGH39; FGS4; CAMGUK; CMG; MICPCH; MRXSNA; TNRC8
Tractability: Small molecule: a structure with a bound ligand is known; a high-quality ligand is known; it has a high-quality binding pocket; it belongs to a druggable protein family. Antibody: its Gene Ontology location is reachable by antibodies, with high confidence; UniProt places it where antibodies can reach, with medium confidence. PROTAC: ubiquitination databases record sites on it; its protein half-life has been measured; a small molecule that binds it is known.
Target class: Enzyme
Chemical probes: NR162 (high quality)
Gene: Protein-coding gene on chromosome X (41,514,934 to 41,923,660, reverse strand). Ensembl gene ENSG00000147044.
Subcellular location: Nucleus; Cytoplasm; Cell membrane
Subcellular location (Human Protein Atlas): Nucleoplasm; Cytosol
Pathways (Reactome):
Neuronal System: Assembly and cell surface presentation of NMDA receptors; Dopamine Neurotransmitter Release Cycle; Neurexins and neuroligins
Sensory Perception: Sensory processing of sound by inner hair cells of the cochlea; Sensory processing of sound by outer hair cells of the cochlea
Cell-Cell communication: Nephrin family interactions
Extracellular matrix organization: Syndecan interactions
Gene Ontology:
Molecular function: protein binding; protein serine kinase activity; protein serine/threonine kinase activity; GMP kinase activity; signaling receptor binding; ATP binding; neurexin family protein binding; protein kinase activity
Biological process: negative regulation of cell-matrix adhesion; negative regulation of cellular response to growth factor stimulus; negative regulation of keratinocyte proliferation; negative regulation of wound healing; cell adhesion; intracellular protein localization; protein transport; regulation of neurotransmitter secretion; GDP metabolic process; GMP metabolic process; regulation of synaptic vesicle exocytosis
Cellular component: basement membrane; cell-cell junction; cytoplasm; focal adhesion; nuclear lamina; nuclear matrix; nucleolus; nucleoplasm; actin cytoskeleton; basolateral plasma membrane; ciliary membrane; cytosol; membrane; nucleus; plasma membrane; presynaptic membrane; cell junction; Schaffer collateral - CA1 synapse; synapse; vesicle
Gene-disease validity (ClinGen):
ClinGen rates the evidence that CASK causes each of these diseases.
X-linked syndromic intellectual disability (X-linked): Definitive.
Homologues: Orthologues: macaque CASK (100% identical), rat Cask (99% identical), chimpanzee CASK (99% identical), dog CASK (99% identical), guinea pig CASK (99% identical), rabbit CASK (99% identical), mouse Cask (99% identical), pig CASK (99% identical), tropical clawed frog cask (99% identical), zebrafish caska (95% identical), zebrafish caskb (48% identical). Paralogues in human: MPP1 (28% identical), MPP2 (25% identical), PALS2 (25% identical), MPP7 (20% identical), MPP3 (19% identical), MPP4 (19% identical), PALS1 (17% identical).
Diseases named in the same sentence as CASK in open-access papers:
CASK is named in the same sentence as 138 diseases in open-access papers, as found by Europe PMC text mining. Sharing a sentence is not in itself a finding about the gene and the disease. The quoted sentences say what the papers report.
microcephaly (45 papers, 2012 to 2026). A congenital or acquired developmental disorder in which the circumference of the head is smaller than normal for the person's age and sex. "Loss-of-function mutations in CASK cause microcephaly with pontine and cerebellar hypoplasia (MICPCH), a severe neurodevelopmental disorder predominantly affecting females." (PMID 41831576, 2026). "Loss‐of‐function variants in the X‐chromosomal gene CASK, which encodes the calcium‐/calmodulin‐dependent serine protein kinase (CASK), are associated with a neurodevelopmental disorder termed microcephaly with pontocerebellar hypoplasia (MICPCH) in females." (PMID 41321276, 2025). "Mutations in CASK cause mental retardation and microcephaly with pontine and cerebellar hypoplasia (MICPCH) syndrome, an XLD disorder." (PMID 40078074, 2025). "So, variants in the CASK gene were mainly the cause of epilepsy with microcephaly, pontine, and cerebellar hypoplasia, and typically affect females." (PMID 37095367, 2023). "Reduced expression of zebrafish CASK caused microcephaly and provided an assay to assess functional changes of human mutations." (PMID 37805506, 2023). "Human CASK mutations cause microcephaly and short stature, which co-occur in a subset of monogenic neurodevelopmental disorders with intellectual disability." (PMID 37805506, 2023). "In particular, heterozygous and hemizygous LoF variants in CASK lead to microcephaly with pontine and cerebellar hypoplasia (MICPCH [MIM: 300749])." (PMID 35830857, 2022). "Loss-of-function variants in the X-chromosomal CASK gene lead to microcephaly with pontine and cerebellar hypoplasia (MICPCH) and intellectual disability (ID) in females in the heterozygous state and in males in the hemizygous state." (PMID 36137748, 2022). "CASK variants are associated with a wide range of clinical presentations, from lethality and epileptic encephalopathies to intellectual disabilities, microcephaly, and autistic traits." (PMID 35406695, 2022). "MICPCH (microcephaly and pontocerebellar hypoplasia) is a monogenic condition that results from variants of an X-linked gene, CASK (calcium/calmodulin-dependent serine protein kinase)." (PMID 35406695, 2022). "Disruption of the CASK-Neurexin interaction was recently proposed to be strictly linked to microcephaly onset in CASK-mutated patients." (PMID 33925474, 2021). "This region contains the CASK gene, whose deletion has been associated with mental retardation and microcephaly with disproportionate pontine and cerebellar hypoplasia in females." (PMID 33584783, 2020). "Genetic variants in CASK were first described in cases with microcephaly with pontine and cerebellar hypoplasia (MICPCH), followed by the identification in cases with X-linked ID (XL-ID), developmental delay (DD), and ASD1,4–6." (PMID 32929080, 2020). "In fact, both of the girls reported to have the heterozygous CASK R27* mutation exhibited microcephaly, pontocerebellar hypoplasia, and profound intellectual disability, but no seizures." (PMID 32696595, 2020). "Mutations of CASK have beenassociated with intellectual disability, microcephaly and cerebellar hypoplasia." (PMID 31356645, 2019). "The Xp11.4 deletion resulted in loss of the first exon and 5′ UTR region of the CASK gene, which is associated with a known X-linked dominant genetic syndrome of mental retardation and microcephaly with pontine and cerebellar hypoplasia." (PMID 31312255, 2019). "Loss-of-function mutations of CASK are associated with intellectual disability and microcephaly with pontine and cerebellar hypoplasia (MICPCH), especially in females." (PMID 28783747, 2017). "Mutations in the X-linked (XLID) gene CASK are associated with mental retardation and microcephaly with pontine and cerebellar hypoplasia (MICPCH; OMIM# 300749)." (PMID 29258560, 2017). "(i) Child A (54 months of age) has a variant in CASK gene (NM_003688) c.2221 + 1G > C with microcephaly and mild hypoplasia of the pons and cerebellum." (PMID 29258560, 2017).
microcephaly (continued). "Mutations in the X-linked intellectual disability gene (XLID) CASK is one etiology associated with microcephaly which produces mental retardation and microcephaly with pontine and cerebellar hypoplasia (MICPCH; OMIM# 300749)." (PMID 29258560, 2017). "Subjects with mutations in CASK exhibit autistic traits, intellectual disability, Ohtahara syndrome, infantile spasms, FG syndrome, mental retardation and microcephaly with pontine and cerebellar hypoplasia (MICPCH)." (PMID 27036546, 2016). "Mutations in the CASK gene cause mental retardation with microcephaly and pontocerebellar hypoplasia." (PMID 26846091, 2016). "A large component of CASK-associated pathology develops postnatally, which has been reported by some authors as postnatal microcephaly or even atrophy." (PMID 27036546, 2016). "Heterozygous loss-of-function mutations in the X-linked CASK gene cause progressive microcephaly with pontine and cerebellar hypoplasia (MICPCH) and severe intellectual disability (ID) in females." (PMID 25886057, 2015). "PCH is most often autosomal recessive though de novo anomalies in the X-linked gene CASK have recently been identified in patients, mostly females, presenting with intellectual disability, microcephaly and PCH (MICPCH)." (PMID 22452838, 2012). "This patient exhibited microcephaly as well as intellectual disability, suggesting that the CASK gene may be involved in X-linked intellectual disability (XLID)." (PMID 37628707, 2023). "Notably, missense mutations associated with epilepsy and intellectual disability were found throughout the whole region of the CASK protein, while missense mutations related to microcephaly and MICPCH were restricted in certain domains." (PMID 37628707, 2023). "Because microcephaly in CASK-linked pathology progresses postnatally, there may be a temporal window when therapeutic intervention might prevent or slow further brain cell loss." (PMID 35406695, 2022). "CASK heterozygous mutations in female patients associate with intellectual disability, microcephaly, pontocerebellar hypoplasia, and optic nerve hypoplasia, whereas CASK hemizygous mutations in males manifest as early infantile epileptic encephalopathy with a grim prognosis." (PMID 32696595, 2020). "Future studies should investigate these pathways in more detail and characterize how they might be linked to CASK-related phenotypes, including microcephaly, scoliosis, and abnormalities of the eye and skin development." (PMID 32929080, 2020). "In humans, mutations in CASK cause mental retardation as a result of microcephaly." (PMID 31289196, 2019). "In mammals, the high metabolic demand of the growing neonatal brain could explain the lethality and postnatal onset of microcephaly and cerebellar hypoplasia in cases of CASK deficiency." (PMID 27036546, 2016). "However, we concluded that the CASK mutation of the sister was de novo because her mother did not possess any phenotypes caused by CASK mutations, including intellectual disability, ataxic gait, or microcephaly." (PMID 31044082, 2019). "Finally, all girls and boys with inactivating CASK mutations presented with a recognizable phenotype characterized by severe postnatal microcephaly, moderate to severe motor and intellectual disability, feeding and sleep difficulties, frequent ophthalmological anomalies and PCH on MRI." (PMID 22452838, 2012). "Pathogenic CASK variants are associated with neurodevelopmental disorders of variable severity including X-linked intellectual disability (XLID) and microcephaly with pontocerebellar hypoplasia (MICPCH)." (PMID 41039189, 2025). "The combination of microcephaly, a form of 'short stature', and impaired cognition represents strong face validity of the Drosophila model of CASK-related disorders." (PMID 37805506, 2023). "MICPCH/microcephaly is one of the phenotypes of CASK-related disorders that has been extensively examined in animal models." (PMID 37628707, 2023).
microcephaly (continued). "Among children with CASK-related disorders, progressive postnatal microcephaly has been extensively documented." (PMID 37805506, 2023). "CASK mutants also have smaller heads than their genetic controls (p < 0.001); in other words, CASK-LOF mutants have microcephaly." (PMID 37805506, 2023). "Microcephaly with pontine and cerebellar hypoplasia (MICPCH) syndrome is the severest form of CASK deficient disorder in which many of these symptoms are associated with microcephaly and pontocerebellar hypoplasia." (PMID 37190086, 2023). "In patients with CASK-related disorders, microcephaly has been shown to be progressive from the prenatal period." (PMID 37628707, 2023). "CASK is an excellent candidate gene for microcephaly disproportionate pontine and cerebellar hypoplasia (MICPCH) (MIM# 300749) since this gene functions in neuronal development." (PMID 35668446, 2022). "Both of our detected patients showed microcephaly with bilateral cerebellar hemispheres and brain stem decreased volume, which was considered to be relevant to the disruption of the CASK‐neurexin interaction." (PMID 36168867, 2022). "MD-208 (heterozygous CASK c.2589+2T>G), a 5-year-old girl, also had congenital microcephaly with PCH and generalised CA." (PMID 36233161, 2022). "One boy who carried the p.E115K variant and died at an early age showed pontocerebellar hypoplasia (PCH) in addition to microcephaly, thus exhibiting the classical MICPCH phenotype observed in individuals with CASK loss-of-function variants." (PMID 36137748, 2022). "MICPCH (microcephaly and pontocerebellar hypoplasia), a monogenic pediatric brain disorder, is associated with variants of CASK (calcium/calmodulin-dependent serine protein kinase)." (PMID 35406695, 2022). "The human CASK gene is located on the X chromosome; patients with mutations in CASK exhibit X-linked intellectual disability (XLID) and microcephaly with pontine and cerebellar hypoplasia (MICPCH)." (PMID 34133460, 2021). "Mutations in the X‐linked gene CASK (OMIM: 300172) are associated with intellectual disability, microcephaly and pontocerebellar hypoplasia." (PMID 32696595, 2020). "Mutations in CASK are known to result in microcephaly with pontocerebellar hypoplasia and severe intellectual disability, further evidence that KIRREL3 and CASK play a critical role in neurodevelopment." (PMID 29271092, 2018). "(ii) Child B (89 months of age) has p.Arg537Ter (CGA > TGA): c.1609 C > T in exon 17 in the CASK gene (NM_003688.3) with microcephaly, and the right cerebellar hemisphere is smaller than the left." (PMID 29258560, 2017). "Mutations within the CASK gene on the X-chromosome have been identified in human patients presenting severe neurological defects, microcephaly and mental impairments, highlighting an essential role of the CASK protein during the brain development." (PMID 27199730, 2016). "We recommend CASK testing in male patients with the combination of DD/ID or epileptic encephalopathy, postnatal microcephaly (< −3 SD) and pontocerebellar hypoplasia." (PMID 25886057, 2015). "Using Array-CGH, two groups identified Xp11.4 submicroscopic deletions involving the CASK gene in girls affected with intellectual disability and microcephaly." (PMID 22452838, 2012). "Microcephaly with pontine and cerebellar hypoplasia (MICPCH) syndrome is a severe neurodevelopmental disorder caused by a deficiency in the X-linked gene calcium/calmodulin-dependent serine protein kinase (CASK)." (PMID 40422253, 2025). "The genomic deletions described in this report include genes other than the CASK gene, and it was not concluded that the CASK gene was the cause of microcephaly and XLID." (PMID 37628707, 2023). "The subject described here, a male with CASK R27* null mutation, shares similarities with the previously reported case in having short stature, seizures with EEG abnormalities, severe pontocerebellar hypoplasia, and microcephaly." (PMID 32696595, 2020).
microcephaly (continued). "Since 2008, when both a heterozygous deletion and point mutations affecting CASK were reported to cause intellectual disability and microcephaly with pontine and cerebellar hypoplasia (MICPCH, OMIM: #300749), various types of CASK aberrations have been reported in more than 50 MICPCH patients." (PMID 28783747, 2017). "However, pronounced microcephaly was observed beginning one week after birth, and the brains of adult CASK(+/-) females were ~ 25 % smaller in weight compared to sex-matched wild-type littermate controls." (PMID 27036546, 2016). "Surprisingly, the observed microcephaly in CASK(+/-) mice is not simply due to loss of only the CASK null cells i.e. it occurs in a non-cell autonomous manner." (PMID 27036546, 2016). "More recently de novo anomalies in the X-linked gene CASK (calcium/calmodulin-dependent serine protein kinase) have been identified in patients with PCH, mostly females, displaying intellectual disability and microcephaly (MICPCH syndrome)." (PMID 22452838, 2012). "In some cases, CASK variants have been associated with microcephaly without cerebellar hypoplasia." (PMID 35406695, 2022). "Moreover, DLGAP2 interacts with NRXN1, a pre-synaptic cell-adhesion molecule and CASK, another scaffolding protein and mutations in both NRXN1 and CASK are associated to neurodevelopmental and neurocognitive disabilities and microcephaly." (PMID 33925474, 2021). "Altogether, these data suggest that although loss of CASK function in neurons contributes to some components of the phenotypic spectrum of CASK-associated pathology (e.g. growth retardation and epilepsy), it does not contribute to microcephaly or cerebellar hypoplasia." (PMID 27036546, 2016). "Mutations in human CASK can lead to a number of neurological diseases including FG syndrome 4, X-linked mental retardation with or without nystagmus and intellectual disability and microcephaly with pontine and cerebella hypoplasia." (PMID 24062638, 2013). "However, it may be distinguished from typical MICPCH caused by CASK mutation by a relatively milder microcephaly, thicker corpus callosum and non-atrophic brainstem." (PMID 28783747, 2017). "Many CASK missense mutations in human males are associated with intellectual disabilities and growth retardation in the absence of microcephaly, clearly indicating that these phenotypes are not interdependent and may represent loss of different molecular functions of CASK." (PMID 27036546, 2016). "Our data further indicates that although CASK is a cytosolic protein and may perform cell-autonomous function in regulating metabolism, CASK-linked microcephaly occurs in a non-cell autonomous manner which involves loss of both CASK positive and CASK null cells." (PMID 27036546, 2016). "We therefore next sought to determine if the microcephaly in CASK(+/-) mice was due to a reduction in cell number in a non-cell-autonomous manner." (PMID 27036546, 2016). "Indeed, analysis of several types of transgenic CASK-mutant mice implicate non-neuronal cells as contributors to microcephaly." (PMID 37805506, 2023). "In other cases, the phenotypes do not fit neatly into either category, including autism spectrum disorder (ASD) without ID in males or females, progressive microcephaly without cerebellar/pontine abnormalities, or focal cortical dysplasia in a female with a large somatic CASK-mutant clone." (PMID 37805506, 2023). "Microcephaly is a co-morbidity of several other PCH types and not unique to CASK variants." (PMID 35406695, 2022). "Our findings demonstrate that MICPCH is a genetically heterogeneous condition, in which CASK inactivating mutations appear to account for the majority of MICPCH cases and with severer phenotypes, while the non-CASK mutation cases tend to have milder microcephaly." (PMID 28783747, 2017).